THRB (thyroid hormone receptor beta)
Diseases named in the same sentence as THRB in open-access papers (continued):
Sharing a sentence is not in itself a finding about the gene and the disease.
pituitary adenoma (3 papers, 2020 to 2024). "Here, we report a 54-year-old woman with RTHβ who was misdiagnosed with a TSH-secreting pituitary adenoma caused by a His435Arg pathogenic variant in the THRB gene." (PMID 39091608, 2024). "In addition, a somatic mutation of THRβ was found in a TSH-secreting pituitary adenoma in one of the patients included in our study." (PMID 36843601, 2023).
renal carcinoma (3 papers, 2012 to 2016). A carcinoma arising from the epithelium of the renal parenchyma or the renal pelvis. "This regulation, together with previously reported altered splicing and mutations in THRB could directly lead to deregulation of thyroid receptor beta in renal cancer." (PMID 24849932, 2014). "Real-time PCR analysis performed on cDNA from kidney cell lines confirmed decreased expression of THRB in renal cancer." (PMID 24849932, 2014). "In conclusion, we identified two novel microRNAs, miR-155 and miR-425, that target THRB transcript and downregulate its expression in renal cancer." (PMID 24849932, 2014). "Recently, the activity of THRB as a tumour suppressor has been reported, which is correlated with a reduced THRB expression found in renal cancer." (PMID 23781307, 2012). "Since epigenetic regulation is a common mechanism influencing the expression of tumor suppressors, we hypothesized that downregulation of THRB in renal cancer results from epigenetic aberrances, including CpG methylation and microRNA-dependent silencing." (PMID 24849932, 2014). "Which of these mechanisms can affect THRB expression in renal cancer is currently unknown." (PMID 24849932, 2014). "In this study, using three different methods, we showed that in the analyzed samples of renal cancer aberrant THRB expression does not result from tumor-specific changes in DNA methylation of THRB promoter region." (PMID 24849932, 2014). "Although THRB expression did not seem to be influenced by DNA methylation in our renal cancer samples, treatment of UOK171 cell line with 5-aza-2′ deoxycytidine resulted in increased expression of THRB gene." (PMID 24849932, 2014). "In contrast, CpG methylation is rather not the main mechanism directly contributing to deregulated THRB expression in renal cancer." (PMID 24849932, 2014).
schizophrenia (3 papers, 2016 to 2025). A major psychotic disorder characterized by abnormalities in the perception or expression of reality. "Also, candidate gene studies have reported associations between schizophrenia and THRB, COMT, DIXDC1, and WBP1L." (PMID 38503926, 2024). "The gain of power is due to multiple small independent association signals at these loci (e.g. the THRB and FOXP1 loci for schizophrenia)." (PMID 27604177, 2016). "Notable examples include SYK for AD and THRB for schizophrenia." (PMID 40502754, 2025).
thyroid (3 papers, 2012 to 2025). "The thyroid hormones triiodothyronine (T3) and thyroxine (T4) stimulate both hepatic lipogenesis and lipolysis by binding to thyroid hormone receptors α (THRα) and β (THRβ), although THRβ is the largely prevalent isoform in the liver." (PMID 40217851, 2025).
clear cell renal carcinoma (2 papers, 2014 to 2022). A malignant epithelial neoplasm of the kidney characterized by the presence of lipid-containing clear cells within a vascular network. "Our previous studies revealed downregulation of THRB in clear cell renal cell carcinoma (ccRCC), but the culpable mechanisms have not been fully elucidated." (PMID 24849932, 2014).
colon cancer (2 papers, 2012 to 2018). "In particular, the THRB gene is frequently methylated, and its expression is strongly decreased, in colon cancer." (PMID 30123421, 2018).
follicular thyroid adenoma (2 papers, 2014 to 2024). A benign, encapsulated tumor, arising from the follicular cells of the thyroid gland. "In contrast to Patient #4, who presented with oligogenic variants of DUOX2, THRB, and TPO and underwent continuous follow-up owing to a simple goiter, Patient #15 had an enlarged nodular goiter and was finally diagnosed with thyroid follicular adenoma." (PMID 39029043, 2024).
Hearing impairment (2 papers, 2021 to 2025). A decreased magnitude of the sensory perception of sound. "Studiesinvolving THRB-knockout mice and subjects homozygous for THRB variants havedemonstrated this association with severe hearing impairment." (PMID 39945573, 2025).
Insulin resistance (2 papers, 2021 to 2026). Increased resistance towards insulin, that is, diminished effectiveness of insulin in reducing blood glucose levels. "As insulin resistance is closely associated with this disease, it is crucial that we understand the role of hepatic THRβ in glucose homeostasis." (PMID 42118980, 2026).
lung carcinoma (2 papers, 2014 to 2023). "In lung cancer, it has been reported that THRB is genetically inactivated due to abnormal methylation." (PMID 37667226, 2023). "Hypermethylation of THRB promoter was reported in several neoplasms, including breast, thyroid and lung cancers and leukemia." (PMID 24849932, 2014).
melanoma (2 papers, 2015 to 2024). A malignant, usually aggressive tumor composed of atypical, neoplastic melanocytes. "Indeed, loss of THRB gene expression has been described in many malignancies, including lung, melanoma, breast, head and neck, kidney, cervix, ovarian and testicular cancers." (PMID 39682255, 2024). "Finally, we constructed a curated transcription factor (TF) and miRNA coordinated regulatory network, from which we identified downstream regulatory cascades initiated by three concordantly hypomethylated and up-regulated genes (PDGFD, ZEB1, and THRB) in NRASQ61-mutated melanomas." (PMID 25537510, 2015). "Furthermore, in order to evaluate the therapeutic potentials of PDGFD, ZEB1, and THRB, we obtained 413 melanoma samples with clinical information and gene expression from TCGA." (PMID 25537510, 2015).
mesothelioma (2 papers, 2013 to 2015). A usually malignant and aggressive neoplasm of the mesothelium which is often associated with exposure to asbestos. "Most of these SNPs were located in regions reported to harbor aberrant alterations in mesothelioma (SLC7A14, THRB, CEBP350, ADAMTS2, ETV1, PVT1 and MMP14 genes), causing at most a 2–3-fold increase in MPM risk." (PMID 23626673, 2013).
osteoporosis (2 papers, 2010 to 2025). A condition of reduced bone mass, with decreased cortical thickness and a decrease in the number and size of the trabeculae of cancellous bone (but normal chemical composition), resulting in increased fracture incidence. "We identify Thyroid Hormone Receptor Beta (Thrb) and Protein Kinase C Zeta (Prkcz) as potential therapeutic targets for the treatment of osteoporosis." (PMID 40204733, 2025).
pituitary tumor (2 papers, 2014 to 2023). A benign or malignant neoplasm affecting the pituitary gland. "This study shows that patients with both RTH and pituitary tumors have multiple clinical manifestations and different thyroid functions, imaging characteristics of pituitary tumors, genetic mutations of THRβ, and treatments." (PMID 36843601, 2023). "Patients with both RTH and pituitary tumors had multiple clinical manifestations and different thyroid functions, imaging characteristics of pituitary tumors, genetic mutations of THRβ, and treatments." (PMID 36843601, 2023). "In our patient, the elevated levels of thyroid hormones (FT3 and FT4) with normal levels of TSH, exclusion of a pituitary tumor by magnetic resonance imaging and the presence of a rare mutation, p.Ala268Gly, in THRβ support the diagnosis of RTH." (PMID 24393243, 2014). "Summary of the THRβ mutations of RTH patients coexistent with pituitary tumor." (PMID 36843601, 2023).
retinal degeneration (2 papers, 2023). Degeneration of the retina. "Here, we have expanded the phenotype of THRB with the identification of a putatively spliceogenic variant associated with retinal degeneration, as the main clinical outcome in three unsolved IRD families." (PMID 37547476, 2023).
testicular cancer (2 papers, 2023 to 2024). A primary or metastatic malignant neoplasm that affects the testis. "The GO term ‘cellular response to chemical stimulus’ includes the thyroid hormone receptor beta (THRB) gene, which has been observed in lung, skin, breast, head and neck, renal, cervical, ovarian, and testicular cancer." (PMID 37667226, 2023).
thyroid tumor (2 papers, 2022 to 2023). A benign or malignant neoplasm affecting the thyroid gland. "On the other side, both in vitro and in vivo experiments confirmed a delayed progression of thyroid tumors when the repressed THRB was rescued." (PMID 37264363, 2023). "To explore the clinical significance of the antagonistic activity of BDE209 on TRß in human thyroid tumours, we analysed the expression of THRB in multiple publicly accessible datasets." (PMID 35681752, 2022). "THRB expression was significantly decreased in thyroid tumour samples compared with that of the corresponding normal thyroid samples, as shown in different gene expression profile data." (PMID 35681752, 2022).
abortion (1 paper, 2023). the ending of pregnancy by removing a fetus or embryo before it can survive outside the uterus. "The expression of thyroid hormone receptors (THRα and THRβ) in placenta villi and decidual tissues in spontaneous abortion and recurrent spontaneous abortion was downregulated." (PMID 37968664, 2023).
attention deficit-hyperactivity disorder (1 paper, 2025). A disorder characterized by a marked pattern of inattention and/or hyperactivity-impulsivity that is inconsistent with developmental level and clearly interferes with functioning in at least two settings (e.g. at home and at school). "But about one-half of patients with THRB mutations have learning disabilities, and a low IQ (<60) can be present in ~3% of cases; ~50% of the children carriers of TRβ mutations are diagnosed with attention deficit hyperactivity disorder." (PMID 40463237, 2025).
Central hypothyroidism (1 paper, 2024). A type of hypothyroidism due to an insufficient stimulation of an otherwise normal thyroid gland. "The mechanism underlying central hypothyroidism induced by HIF-PH inhibitors has been elucidated as follows: roxadustat, owing to its structural similarity to T3, crosses the blood-brain barrier and interacts with the pituitary thyroid hormone receptor (THRβ)." (PMID 38975517, 2024).
cone dystrophy (1 paper, 2023). An inherited ocular disorder characterized by the loss of cone cells, the photoreceptors responsible for both central and color vision. "Similarly, likely pathogenic variants in the THRB gene, especially in the TRβ1 specific exons, should also be considered as disease-causing in patients with clinically diagnosed macular dystrophies, cone-dystrophy, or Stargardt disease with or without extra-ocular manifestations." (PMID 37547476, 2023).
deafness (1 paper, 2021). An inherited or acquired condition characterized by the complete loss of the ability to hear from one or both ears. "Actually, THRα1 is considered non-essential for hearing, while defects on THRβ, in mice, present deafness linked to cochlear alterations." (PMID 34447350, 2021).
endometrial tumors (1 paper, 2020). "Since THRB is expressed in a majority of DN tumors (103/121, or 85%), THRB could be investigated as a potential therapeutic target within a large subset of DN endometrial tumors that otherwise lack targeted treatment options and have a poor prognosis." (PMID 32894083, 2020).
Fibroadenoma (1 paper, 2011). A benign tumor of the breast characterized by the presence of stromal and epithelial elements. "Conversely, THRβ was significantly higher in fibroadenoma tissue compared to normal (p<0.0001)." (PMID 21283523, 2011). "Human breast tissue specimens (malignant n = 75, normal n = 15, fibroadenoma n = 10) were analysed by RQ-PCR targeting NIS, receptors for retinoic acid (RARα, RARβ), oestrogen (ERα), thyroid hormones (THRα, THRβ), and also phosphoinositide-3-kinase (PI3K)." (PMID 21283523, 2011). "It is interesting to note that the 3 genes in this study found to be differentially expressed in fibroadenoma and malignant tissue (NIS, RARβ and THRβ), have all been suggested to have tumour suppressor roles." (PMID 21283523, 2011). "Total RNA extracted from malignant (n = 75), normal (n = 15), and fibroadenoma (n = 10) breast tissue biopsies was analysed using RQ-PCR targeting NIS, RARα, RARβ, ERα, PI3K, THRα and THRβ." (PMID 21283523, 2011).
germinoma (1 paper, 2010). A malignant germ cell tumor arising in the central nervous system. "In the germinoma group, the expression levels of RUNX1T1 and THRB were inversely correlated with expression of miR-146a, and the levels of NRP1, SVIL and PDGFRA were inversely correlated with the expression of miR-142-5p." (PMID 20178649, 2010).
in in situ carcinoma (1 paper, 2020). "Nonetheless, in another study, THRβ was described as being expressed in nuclei of proliferative cells, in in situ carcinoma, and in the cytoplasm in normal breast and in infiltrative BC cells." (PMID 31947762, 2020).
Intellectual disability (1 paper, 2024). "Rare cases with homozygous deletion or variants in THRB exhibit features including dysmorphic facies and audiovisual abnormalities or intellectual disability, tachyarrhythmias, and thyrotoxic cardiomyopathy." (PMID 38963712, 2024).
leukemia (1 paper, 2014). A malignant (clonal) hematologic disorder, involving hematopoietic stem cells and characterized by the presence of primitive or atypical myeloid or lymphoid cells in the bone marrow and the blood. "Several other studies suggested DNA hypermethylation as a mechanism contributing to THRB silencing in leukemia and cancers of breast, lung, and thyroid." (PMID 24849932, 2014).
liver cancer (1 paper, 2024). An epithelial or non-epithelial malignant neoplasm that arises from the liver. "Robust positive correlations are evident with key hormonal markers such as AR (ρ = 0.668), ESR1 (ρ = 0.547), and THRB (ρ = 0.424), underscoring the intricate involvement of SELENOP in hormonal pathways within the realm of liver cancer." (PMID 39001444, 2024).
lung fibrosis (1 paper, 2024). "Immunohistochemistry results showed that the expression of thyroid hormone receptors THRα and THRβ in the fibrotic areas of the lung increased in mice with lung fibrosis after BLM treatment." (PMID 39323641, 2024).
lymph node metastasis (1 paper, 2022). "The data from GSE60542 also demonstrated that THRB was significantly downregulated in lymph node metastasis compared with the corresponding normal thyroid tissue." (PMID 35681752, 2022).
migraine (1 paper, 2018). "The microarray analysis implicated thyroid hormone receptor beta which had been previously associated with migraine, and chemokine signalling (Ccr7), among many others as well as long non-coding RNAs (lncRNA) putatively involved in gene regulation." (PMID 29997476, 2018).
Miscarriage (1 paper, 2023). A pregnancy that ends at a stage in which the fetus is incapable of surviving on its own, defined as the spontaneous loss of a fetus before the 22th week of pregnancy. "The expression of THRα, but not THRβ, was significantly decreased in the placental villi of miscarriage patients." (PMID 37968664, 2023). "Accordingly, the protein abundance of THRα in villi was also significantly downregulated in the miscarriage group, but not the protein abundance of THRβ." (PMID 37968664, 2023). "Surprisingly, we found that the expression of THRβ was not different between the miscarriages and ETP group." (PMID 37968664, 2023). "The protein abundances of TTR and THRα were downregulated in miscarriage group, but not THRβ." (PMID 37968664, 2023). "In miscarriage group, the gene expression of Dio2, Dio3, TTR and THRα, but not THRβ, MCT8 and OATP1A1, were downregulated." (PMID 37968664, 2023).
multinodular goiter (1 paper, 2022). Nodular goiter characterized by more than one discrete tissue mass. "Patient 2 is a 32-year-old pregnant woman with multinodular goiter, and the THRβ heterozygous variant c.959G>C, that, to the best of our knowledge, has been reported in literature only once." (PMID 36232568, 2022).
myocardial hypertrophy (1 paper, 2024). "Reports indicate THRB's regulation of genes linked to myocardial hypertrophy, including Myh6, Adrb1 and Atp2a2,28, 29 highlighting its role in myocardial remodelling and explaining the downregulation of HINT2 expression." (PMID 38546629, 2024).
non-Hodgkin lymphoma (1 paper, 2015). Distinct from Hodgkin lymphoma both morphologically and biologically, non-Hodgkin lymphoma (NHL) is characterized by the absence of Reed-Sternberg cells, can occur at any age, and usually presents as a localized or generalized lymphadenopathy associated with fever and weight loss. "Further functional studies will be performed in order to confirm the function of this THRB mutation in RTH or non-Hodgkin’s lymphoma." (PMID 25621029, 2015). "The present case indicated that the point mutantion of THRB in 3′-UTR might be an important indicator for RTH or non-Hodgkin’s lymphoma." (PMID 25621029, 2015). "Whether or not the mutation of THRB increases the morbidity of non-Hodgkin’s lymphoma or LPL remains unclear." (PMID 25621029, 2015).
retinal disease (1 paper, 2025). "An example of the potential of PMM in research has been highlighted by its application in variant screening of the newly identified retinal disease gene (THRB) in unsolved cases of inherited retinal dystrophies, further reinforcing the need for constant updates of virtual panels." (PMID 39833864, 2025).
schistosomiasis (1 paper, 2012). An infectious disease caused by parasitic trematodes of the genus Schistosoma that colonize human blood vessels and release eggs that can cause granulomatous reactions leading to acute (swimmer's itch or acute schistosomiasis syndrome) or chronic disease. "The purpose of this study was to identify a novel thyroid hormone receptor beta encoding gene of Schistosoma japonicum (SjTHRβ) and to investigate its potential as a vaccine candidate antigen against schistosomiasis in BALB/c mice." (PMID 22889153, 2012).
TSHomas (1 paper, 2020). "TSH secreting pituitary adenomas (TSHomas) and Resistance to Thyroid Hormone due to mutations in the THRB gene (RTHβ) are two possible underlying causes of the rare clinical entity of inappropriate secretion of TSH (IST), which is characterized by hyperthyroxinemia and non-suppressed TSH levels." (PMID 32733382, 2020).
Visual impairment (1 paper, 2023). "However, monoallelic or biallelic THRB variants have only been associated with generalized or selective pituitary RTHβ in humans, with just a few patients showing visual impairment." (PMID 37547476, 2023).